TAX1BP1 (Tax1 binding protein 1)
Description:
Ubiquitin-binding adapter that participates in inflammatory, antiviral and innate immune processes as well as selective autophagy regulation. Plays a key role in the negative regulation of NF-kappa-B and IRF3 signalings by acting as an adapter for the ubiquitin-editing enzyme A20/TNFAIP3 to bind and inactivate its substrates. Disrupts the interactions between the E3 ubiquitin ligase TRAF3 and TBK1/IKBKE to attenuate 'Lys63'-linked polyubiquitination of TBK1 and thereby IFN-beta production. Also recruits A20/TNFAIP3 to ubiquitinated signaling proteins TRAF6 and RIPK1, leading to their deubiquitination and disruption of IL-1 and TNF-induced NF-kappa-B signaling pathways. Inhibits virus-induced apoptosis by inducing the 'Lys-48'-linked polyubiquitination and degradation of MAVS via recruitment of the E3 ligase ITCH, thereby attenuating MAVS-mediated apoptosis signaling. As a macroautophagy/autophagy receptor, facilitates the xenophagic clearance of pathogenic bacteria such as Salmonella typhimurium and Mycobacterium tuberculosis. Upon NBR1 recruitment to the SQSTM1-ubiquitin condensates, acts as the major recruiter of RB1CC1 to these ubiquitin condensates to promote their autophagic degradation. Mediates the autophagic degradation of other substrates including TICAM1.
Synonyms: T6BP; TXBP151; CALCOCO3
Tractability: PROTAC: ubiquitination databases record sites on it; its protein half-life has been measured.
Gene: Protein-coding gene on chromosome 7 (27,739,331 to 27,844,564, forward strand). Ensembl gene ENSG00000106052.
Subcellular location: Cytoplasm; Mitochondrion; Preautophagosomal structure; Cytoplasmic vesicle, autophagosome
Subcellular location (Human Protein Atlas): Cytosol; Nucleoplasm
Pathways (Reactome):
Immune System: Negative regulators of DDX58/IFIH1 signaling
Signal Transduction: Regulation of TNFR1 signaling
Gene Ontology:
Molecular function: protein binding; protein-macromolecule adaptor activity; signaling adaptor activity; kinase binding
Biological process: negative regulation of cytoplasmic pattern recognition receptor signaling pathway; negative regulation of interleukin-1-mediated signaling pathway; negative regulation of toll-like receptor 4 signaling pathway; negative regulation of tumor necrosis factor-mediated signaling pathway; protein localization to phagocytic vesicle; negative regulation of apoptotic process; negative regulation of canonical NF-kappaB signal transduction
Cellular component: cytoplasm; extracellular exosome; mitochondrion; phagophore assembly site; cytosol; autophagosome
Genetic constraint (gnomAD): Loss-of-function variants: 56 observed, 88.95 expected, observed/expected ratio (o/e) 0.63, 90% interval 0.51 to 0.79. The upper end of that interval is the gene's LOEUF score, 0.79, which puts it in group 3 of 6, group 1 being the genes least tolerant of losing a copy. Missense variants: 840 observed, 913.81 expected, observed/expected ratio (o/e) 0.92, 90% interval 0.87 to 0.97. Synonymous variants: 328 observed, 306.44 expected, observed/expected ratio (o/e) 1.07, 90% interval 0.98 to 1.17.
Homologues: Orthologues: chimpanzee TAX1BP1 (99% identical), macaque TAX1BP1 (96% identical), pig TAX1BP1 (92% identical), rabbit TAX1BP1 (92% identical), guinea pig TAX1BP1 (89% identical), mouse Tax1bp1 (87% identical), dog TAX1BP1 (86% identical), rat Tax1bp1 (84% identical), tropical clawed frog tax1bp1 (62% identical), zebrafish tax1bp1b (52% identical), zebrafish tax1bp1a (47% identical). Paralogues in human: CALCOCO1 (24% identical), CALCOCO2 (17% identical).
Diseases named in the same sentence as TAX1BP1 in open-access papers:
TAX1BP1 is named in the same sentence as 39 diseases in open-access papers, as found by Europe PMC text mining. Sharing a sentence is not in itself a finding about the gene and the disease. The quoted sentences say what the papers report.
viral infection (5 papers, 2013 to 2025). "In conclusion, Tax1bp1-deficiency plays a unique role in controlling host cell death and limiting inflammatory responses during Mtb and Listeria infection, in contrast to the observation that Tax1bp1-deficiency enhances NF-κB signaling during viral infection." (PMID 41171885, 2025). "Furthermore, Tax1bp1-deficiency had an anti-inflammatory function during Mtb and Listeria animal infection, compared to its pro-inflammatory phenotype in viral infections." (PMID 41171885, 2025). "Tax1bp1 was previously shown to negatively regulate apoptosis following cytokine stimulation and viral infection." (PMID 41171885, 2025). "Tax1bp1 was previously shown to regulate apoptosis following cytokine stimulation and viral infection." (PMID 39763950, 2024). "Recently, TAX1BP1 has been shown to play an important role in negatively regulating the VSV and Sendai virus associated apoptosis, as it gets degraded upon viral infection." (PMID 30483501, 2018). "Together, this study suggests that RNF11 is a novel inhibitor of antiviral signaling that cooperates with TAX1BP1 to restrict IFN production during virus infection." (PMID 23308279, 2013). "In conclusion, Tax1bp1 plays a unique role in controlling host cell death and promoting inflammatory responses during Mtb and Listeria infection in contrast to its function in terminating NF-κB signaling during viral infection." (PMID 39763950, 2024). "Furthermore, Tax1bp1 had a pro-inflammatory function during Mtb and Listeria animal infection, compared to its anti-inflammatory role in viral infections." (PMID 39763950, 2024). "Moreover, TAX1BP1 expression was shown to strongly block IFNβ activation mediated by virus infection, and TAX1BP1 overexpression blocked NF-κB activation." (PMID 36248895, 2022). "Few reports also manifest anti-inflammatory roles of TAX1BP1 during other viral infections." (PMID 30483501, 2018). "It is also unclear what regulates the interactions between A20, TAX1BP1, ABIN1 and RNF11 during virus infection to assemble the A20 antiviral complex." (PMID 23308279, 2013).
breast carcinoma (3 papers, 2012 to 2024). "A variety of solid tumors have been reported to overexpress TAX1BP1, including breast cancer, lung cancer, and liver cancer." (PMID 38167446, 2024). "Four of the ten closest genes with probes available showed moderate association with breast cancer survival at P < 0.005 (HOXA9, HOTTIP, EVX1 and TAX1BP1), with these associations mainly observed for ER-negative breast cancer." (PMID 30787463, 2019). "Other researchers have reported associations of RNF11 with glutathione S-transferase -tagged Itch in breast cancer cell lines, tagged RNF11 with tagged TAX1BP1 and A20 in HEK cells and RNF11 with A20, TAX1BP1 and RIP1 in mouse embryonic fibroblasts and blood-derived macrophages." (PMID 22507528, 2012).
gastric cancer (3 papers, 2015 to 2021). A primary or metastatic malignant neoplasm involving the stomach. "Interestingly, EBV can produce miRNAs, some of which are highly expressed in EBV-associated gastric carcinomas and function to down-regulate expression of e.g., pro- and anti-apoptotic host proteins like Bid and Tax1-binding protein 1 (TAX1BP1), respectively." (PMID 28350359, 2017). "In gastric cancer cell lines, miR-500 directly repressed CYLD, OTUD7B, and the A20 complex component TAX1BP1 which led to sustained NF-κB activation." (PMID 28350359, 2017). "In gastric cancer AGS cell line, viral miR-BART15-3p targets anti-apoptotic TAX1BP1 which promotes cell death and increases chemosensitivity, but simultaneously activates NF-κB, probably by suppressing A20, a TAX1BP1-dependent NF-κB negative regulator." (PMID 28350359, 2017). "Herein, analysis by publicly available algorithms and our serial experimental results demonstrate that CYLD, TAX1BP1, and OTUD7B are bona fide targets of miR-500 in gastric cancer." (PMID 25595906, 2015). "Taken together, our results suggest that miR-500 overexpression activates the NF-κB signalling pathway by repressing CYLD, TAX1BP1, and OTUD7B, and consequently results in gastric cancer aggressiveness and poor clinical outcomes." (PMID 25595906, 2015). "Lastly, we examined whether miR-500–mediated suppression of CYLD, TAX1BP1, and OTUD7B, and NF-κB activity in gastric cancers are clinically relevant." (PMID 25595906, 2015).
glioma (2 papers, 2023 to 2025). A benign or malignant brain and spinal cord tumor that arises from glial cells (astrocytes, oligodendrocytes, ependymal cells). "In summary, we found in the present study that DPT induced PARP1 over-activation and TAX1BP1 distribution to mitochondria in the glioma cells in vitro and in vivo." (PMID 37186123, 2023). "We showed that treatment with DPT (450 nM) induced PARP1 over-activation and Tax1 binding protein 1 (TAX1BP1) distribution to mitochondria in human U87, U251 and U118 glioma cells." (PMID 37186123, 2023). "These verify that TAX1BP1 is a downstream signal of NAD+ depletion and causes nuclear translocation of AIF in the glioma cells undergoing parthanatos." (PMID 37186123, 2023). "Moreover, DPT-induced mitochondrial depolarization, nuclear translocation of AIF, and glioma cell death were all attenuated when TAX1BP1 was knocked down." (PMID 37186123, 2023). "Therefore, we used DPT in this study to trigger glioma cell parthanatos and investigated whether TAX1BP1 is a downstream signal of activated PARP1 and initiates nuclear translocation of AIF via activation of respiratory complex I." (PMID 37186123, 2023). "Knockdown of TAX1BP1 with siRNA not only inhibited TAX1BP1 accumulation in mitochondria, but also alleviated nuclear translocation of AIF and glioma cell death." (PMID 37186123, 2023). "Knockdown of TAX1BP1 with siRNA not only inhibited TAX1BP1 accumulation on mitochondria, but also alleviated nuclear translocation of AIF and glioma cell death." (PMID 37186123, 2023). "To clarify why over-activated PARP1 could promote TAX1BP1 distribution to mitochondria, we tested the role of NAD+ in DPT-induced glioma cell death considering that it is a substrate of activated PARP1." (PMID 37186123, 2023). "In conclusion, we demonstrated that the NAD+ depletion caused by PARP1 overactivation resulted in mitochondrial translocation of TAX1BP1, which contributed to DPT-induced nuclear translocation of AIF and glioma cell parthanatos via upregulation of mitochondrial complex I activity and assembly." (PMID 37186123, 2023). "Because over-activated PARP1 contributes to DPT-induced glioma cell death, we tested whether PARP1 could regulate TAX1BP1 distribution to mitochondria." (PMID 37186123, 2023).
head and neck cancer (2 papers, 2010 to 2013). A primary or metastatic malignant neoplasm affecting the head and neck. "to assess the T → A polymorphism in gene TAX1BP1 (leu306ile) in patients with head and neck cancer and a control population." (PMID 20549079, 2010). "However, in the case of TAX1BP1 SNPs, only one study has linked them to the head and neck cancer." (PMID 24086273, 2013).
hepatocellular carcinoma (2 papers, 2020 to 2024). A malignant tumor that arises from hepatocytes. "Tax1-binding protein 1 (Tax1BP1) is a regulator of the NFκB signaling pathway, but its role in the liver and hepatocellular carcinoma (HCC) is presently unknown." (PMID 33004985, 2020). "Furthermore enhanced genomic amplification of Tax1BP1 has been described in a subset of hepatocellular carcinomas, which developed in patients with hepatitis C virus infection." (PMID 33004985, 2020).
Listeria infection (2 papers, 2024 to 2025). "Consistent with Tax1bp1 playing a role early in the Listeria infection, we observed a statistically significant difference in Listeria CFU in the spleen, but not yet in the liver, at 4 hours post-infection." (PMID 41171885, 2025). "Consistent with Tax1bp1 playing a role early in the Listeria infection, we observed a statistically significant difference in Listeria CFU in the spleen, but not in the liver, at 4 hours post-infection." (PMID 39763950, 2024).
liver cancer (2 papers, 2020 to 2024). An epithelial or non-epithelial malignant neoplasm that arises from the liver. "We conclude that Tax1BP1 protects from liver cancer development by limiting proinflammatory signaling." (PMID 33004985, 2020). "Nevertheless, the role of Tax1BP1 in liver cancer development is still unknown." (PMID 33004985, 2020).
melanoma (2 papers, 2016 to 2021). A malignant, usually aggressive tumor composed of atypical, neoplastic melanocytes. "Given that TOLLIP, EPS15, and TAX1BP1 were isolated from a human melanoma cell line using a proteomic approach, it stands to reason that other vesicle-associated adaptor proteins expressed in other cell types could exhibit a similar relationship with RNF26." (PMID 27368102, 2016).
pancreatic cancer (2 papers, 2025). "Similarly, exogenous copper has been observed to increase GPX4 ubiquitination and facilitate TAX1BP1 (Tax1 binding protein 1)-dependent GPX4 autophagic degradation, thereby enhancing ferroptosis in pancreatic cancer tumors." (PMID 39856053, 2025).
pancreatic ductal adenocarcinoma (2 papers, 2021 to 2022). An infiltrating adenocarcinoma that arises from the epithelial cells of the pancreas. "Of the four remaining CpGs, according to the EWAS Catalog, one (cg23487201 at APCDD1L) has previously been associated with clear cell carcinoma and pancreatic ductal adenocarcinoma and another (cg00039564 at TAX1BP1) has previously been found to be associated with rheumatoid arthritis." (PMID 33517419, 2021).
Sepsis (2 papers, 2019 to 2023). Sepsis is defined as life-threatening organ dysfunction caused by a dysregulated host response to infection. "Through transcriptomic analysis and comparative analyses using independent scRNAseq datasets, we identified sustained elevation of TAX1BP1 expression in exhausted monocytes from both murine sepsis models and human sepsis patients." (PMID 38162637, 2023). "In four of them, the mean abundance was again higher in sepsis than in SIRS, namely, PPP6R3 (1.7-fold), TAX1BP1 (1.5-fold), DNAJA2 (1.8-fold), and ADRBK1 (1.4-fold)." (PMID 31075840, 2019). "We also put forward PPP6R3, TAX1BP1, and more highly expressed ADRBK1 as new reference genes in SIRS and sepsis NK cells." (PMID 31075840, 2019). "This analysis yielded highly similar expression levels for four of our five candidate reference genes in SIRS and sepsis NK cells, namely, AKIRIN1, PPP6R3, TAX1BP1, and ADRBK1." (PMID 31075840, 2019).
Alzheimer disease (1 paper, 2024). A progressive, neurodegenerative disease characterized by loss of function and death of nerve cells in several areas of the brain leading to loss of cognitive function such as memory and language. "In contrast, Tau fibrils from Alzheimer's disease brains are recognized by p62 but fail to recruit TAX1BP1." (PMID 38865459, 2024).
amyotrophic lateral sclerosis (1 paper, 2023). Amyotrophic lateral sclerosis (ALS) is a neurodegenerative disease characterized by progressive muscular paralysis reflecting degeneration of motor neurons in the primary motor cortex, corticospinal tracts, brainstem and spinal cord. "Therefore, we speculate that the OMM proteins are further ubiquitinated by activated Parkin and recruit mitophagy receptors, including the amyotrophic lateral sclerosis (ALS)-associated protein optineurin (OPTN), NDP52, and TAX1BP1, to a similar extent in control or CPZ-treated cells." (PMID 37745295, 2023).
cardiac failure (1 paper, 2013). "Preliminary electrocardiogram experiments using TAX1BP1-KO mice showed an abnormal prolongation of PQ intervals and/or atrioventricular conduction defects, which might cause fatal cardiac failure." (PMID 24086273, 2013).
cervical cancer (1 paper, 2022). A primary or metastatic malignant neoplasm involving the cervix. "Notably, NDP52 and OPTN, besides TAX1BP1, are the major receptors mediating PINK1-mediated mitophagy in human cervical cancer cell line (HeLa)." (PMID 35305662, 2022).
dermatitis (1 paper, 2013). An inflammatory process affecting the skin. "Genetically engineered TAX1BP1-deficient (KO) mice develop age-dependent inflammatory constitutions in multiple organs manifested as valvulitis or dermatitis and succumb to premature death." (PMID 24086273, 2013). "For research purposes, we established TAX1BP1-deficient (-KO) mice, which display exacerbation of inflammation (characterized as valvulitis and dermatitis) in an age-dependent manner in addition to functional inadequacies manifested in growth retardation and premature death." (PMID 24086273, 2013). "Multiple inflammatory symptoms, including cardiac valvulitis, dermatitis, and a hypersensitive response to endotoxins and inflammatory cytokines, were noted in our preclinical model involving TAX1BP1-KO mice." (PMID 24086273, 2013).
ebola virus disease (1 paper, 2024). "Presently, it is unknown if the VP35-like elements of hamster Tax1bp1 are maintained by evolution or if the expression of TAX1BP1 is affected by ebola virus disease." (PMID 39226335, 2024).
endocarditis (1 paper, 2013). Inflammation of the endocardium. "To test this hypothesis, we examined the link between the commensal microbiota and mitral valvulitis and endocarditis in TAX1BP1-KO mice." (PMID 24086273, 2013). "Since the intrinsic role of Tax1bp1 is to inhibit unnecessarily activated innate immunity responses, a functional deficiency of Tax1bp1 through HTLV-1 infection can lead to similar symptoms in humans; that is, commensal microbiota can cause pseudo-Infective endocarditis symptoms." (PMID 24086273, 2013).
ileitis (1 paper, 2025). "Loss of the autophagy-related gene Atg16l1 inhibited the degradation of TRIF mediated by autophagy receptors SQSTM1 and Tax1BP1, thus driving TRIF-dependent inflammatory signaling in S. Typhimurium-induced ileitis." (PMID 39809743, 2025).
liver fibrosis (1 paper, 2020). "Here we investigated the role of Tax1BP1 in liver cells and murine models of HCC and liver fibrosis." (PMID 33004985, 2020).
muscular disease (1 paper, 2023). Myopathy is a peripheral nervous system disease consisting of any abnormal condition or disease of the muscular tissues; commonly designates a disorder involving skeletal muscle. "This review aims to summarize what has been studied so far about the direct involvement of aggrephagy and the activation of the key players, among others, p62, NBR1, Alfy, Tollip, Optineurin, TAX1BP1 and CCT2 in muscular diseases." (PMID 37176163, 2023).
oral cavity cancer (1 paper, 2010). A primary or metastatic malignant neoplasm involving the oral cavity. "There is evidence of association between TAX1BP1 gene polymorphism and oral cavity cancer." (PMID 20549079, 2010). "There is evidence of this association between the TAX1BP1 gene polymorphism and oral cavity cancer." (PMID 20549079, 2010).